XBP1 (X-box binding protein 1)
Diseases named in the same sentence as XBP1 in open-access papers (continued):
Sharing a sentence is not in itself a finding about the gene and the disease.
diabetes (continued). "As early onset diabetes is a hallmark of Wolfram syndrome, it is highly likely that KDEL receptors are similarly activated through the XBP1 pathway in this disease." (PMID 34063979, 2021). "Surprisingly, TUDCA was able to increase the expression of Atf6 and XBP1 and increased β-cells survival, reduced islet inflammation and thus lower diabetes incidence in mouse models of diabetes." (PMID 33613449, 2020). "The active form of XBP1, which is a major downstream effector of IRE1α, induces NTDs in Xenopus63,64, suggesting that the IRE1α-ER stress pathway is highly relevant to diabetes-induced NTDs." (PMID 30655546, 2019). "One major finding from the current study is that deletion of XBP1 in the retina accelerates retinal function deterioration in diabetes." (PMID 31242599, 2019). "In the present study, we investigated the role of XBP1 in retinal function and structural integrity in experimental diabetes." (PMID 31242599, 2019). "Herein, we induced diabetes with five consecutive daily injections of STZ in XBP1 cKO and WT mice at 8–9 weeks of age." (PMID 31242599, 2019). "Lindenmeyer and colleagues demonstrated that mRNA expression of GRP78/BiP, ORP150/HYOU1, S1P (MBTPS1), calnexin and XBP-1 increase in the kidneys of patients with established diabetes, compared with mild diabetes." (PMID 26239352, 2015). "Accumulating evidence also implicates XBP1 splicing in many disease processes such as cancer, neurodegenerative diseases, and diabetes." (PMID 25530974, 2014). "XBP1 expression is associated with diabetes risk with particular value in under-represented populations at risk of young, non-obese onset diabetes." (PMID 40993285, 2025). "We found that people with a common change in XBP1 had poorer beta-cell function, worse blood sugar control when diagnosed with diabetes, and reduced response to sulphonylurea medications that are used to treat diabetes." (PMID 40993285, 2025). "Primary defects induced by XBP1 deficiency in the absence of diabetes and, thus, independently of glucotoxicity, include beta cell dedifferentiation, beta-to-alpha cell conversion and impaired proinsulin processing." (PMID 35316840, 2022). "Our current study tested this hypothesis and our data support a protective role of XBP1 against retinal neuronal injury and dysfunction induced by diabetes." (PMID 31242599, 2019). "Thus, the retina of XBP1 cKO mice appears and functions identically to WT at the time of onset of diabetes." (PMID 31242599, 2019). "In summary, we have shown that deletion of XBP1 in retinal neurons, and likely some Müller cells, results in accelerated and aggravated neural retinal dysfunction and degeneration, accompanied by enhanced Müller glia activation in diabetes." (PMID 31242599, 2019). "After 6 months of diabetes, both Atf6 and Xbp1 expressions were upregulated in diabetic BMNCs." (PMID 29700294, 2018). "Strategies that augment XBP-1 activity may improve glycemic control and microvascular complications of diabetes." (PMID 26239352, 2015). "In hippocampi from db/db mice, the expression of XBP1s was downregulated at both mRNA and protein levels after 24 weeks of diabetes but not in early diabetes (8 weeks), implying a potential role of XBP1 dysfunction in long-term diabetes-induced cognitive declination." (PMID 25530974, 2014). "The pattern of expression of proteins involved in UPR, namely the PERK (EIF2α, ATF4 and CHOP) and IRE1 (XBP-1) pathways, was different in CDs/y DD from all other groups, with consistently lower levels of expression at 4 weeks after initiation of DD and coinciding with the development of diabetes." (PMID 36674879, 2023). "Additionally, diabetes influenced the expression of ER stress-related genes in the hippocampus, and hippocampal cells adapted to prolonged ER stress induced by T2D with partial suppression of Xbp1." (PMID 31788335, 2019).
diabetes (continued). "We hypothesize that XBP1, which functions as a key regulator of retinal neuronal adaptive mechanism to aging-related stresses, may also play an important role in maintaining retinal neuron function and survival in diabetes." (PMID 31242599, 2019). "The exact function of XBP1 and other UPR pathways in regulation of retinal metabolism during diabetes remains to be elucidated." (PMID 35346303, 2022). "Activation of the IRE1/XBP1 and PERK/ATF4/CHOP pathways differentially regulate retinal endothelial cell death, inflammation, and vascular permeability in animal models of diabetes." (PMID 35346303, 2022). "Our findings suggest an important role of XBP1-mediated adaptive UPR in retinal neuronal survival and function in diabetes." (PMID 31242599, 2019). "Diabetes-increased p-PERK, p-eIF2α, p-IRE1α and CHOP abundance, ER chaperone gene expression and XBP1 cleavage were abrogated in PPARGC1A+ embryos." (PMID 28474670, 2017). "In the present study, we demonstrated that not only CHOP but also other proteins in ER stress cascade, such as GRP-78, XBP-1, ATF-6, are elevated in the hippocampi of animal models of diabetes and primary hippocampal neurons exposed to high glucose." (PMID 27793043, 2016). "Retinal pigment epithelium–specific XBP1 knockout (XBP1RPE−/−) mice were generated in our previous study and induced diabetes by streptozotocin." (PMID 27701635, 2016). "The role of XBP1 expression in maintaining glucose homeostasis, glycaemic control, and response to diabetes therapeutics across human populations has not been previously studied." (PMID 40993285, 2025). "The incidence of TUNEL-positive beta islets in obese β-Xbp1+/+Ob mice was not different from control β-Xbp1+/+Wt mice, suggesting that beta cell apoptosis was not altered in diabetes-resistant ob/ob mice." (PMID 35316840, 2022). "In diabetes, overactivation of UPR leads to phosphorylation of IRE1, which results in degradation of proinsulin mRNA activation of JNK pathway, and splicing of XBP1 mRNA." (PMID 33613449, 2020). "Moreover, in a T1D model mouse at the pre-diabetes stage, expression of UPR mediators, such as ATF6 and Xbp1, were downregulated." (PMID 31822470, 2019). "Likewise, AS-IV markedly reduced diabetes-induced phosphorylation of IRE1α and its downstream target JNK, an apoptosis mediator, and decreased spliced X-box binding protein 1 (XBP1) expression." (PMID 28761152, 2017). "IPA analysis of MAM proteome predicts that XBP1 activation is suppressed, although the level of some individual target proteins is increased; in contrast, the function of PERK/ATF4 pathway is significantly enhanced (p = 6.33E-03) in diabetes." (PMID 28522876, 2017). "Importantly, deletion of XBP1 in Chx10-cre-expressing retinal progenitor cells, which give rise to most retinal neurons and a subset of Müller cells, does not affect retinal function or structure prior to the onset of diabetes nor affects blood glucose or body weight in diabetic mice." (PMID 31242599, 2019). "To further confirm the role of endogenous XBP1 on RPE tight junctions, we examined the tight junctions by immunofluorescent labeling of ZO-1 or using fluor-conjugated phalloidin on RPE whole mounts from XBP1RPE−/− and control mice with or without diabetes." (PMID 27701635, 2016).
triple-negative breast carcinoma (35 papers, 2014 to 2025). An invasive breast carcinoma which is negative for expression of estrogen receptor (ER), progesterone receptor (PR), and human epidermal growth factor receptor 2 (HER2). "In triple-negative breast cancer, XBP1 has been reported to be a pivotal role in the tumorigenicity and progression and XBP1 gene expression was highly associated with HIF1α and hypoxia-driven signatures." (PMID 34094948, 2021). "For example, studies have shown that the homeostatic target of IRE1α, XBP1, promotes tumor progression in models of triple-negative breast cancer cells." (PMID 40278350, 2025). "It has been shown that the homeostatic target of IRE1α, XBP1, promotes tumor progression in models of triple-negative breast cancer cells." (PMID 40278350, 2025). "XBP1 activates numerous genes related to the UPR, and XBP1 activity is linked to GBM growth and survival and promotes growth of triple negative breast cancer in part by reprogramming the cells to an anaerobic metabolism via HIF activated pathways." (PMID 37107600, 2023). "Recent studies showed that HIF-1α was a co-regulator of XBP1 and induced its expression in triple negative breast cancer." (PMID 37752569, 2023). "Previous evidence suggested that XBP1 promoted triple-negative breast cancer by controlling the HIF-1a pathway." (PMID 35915851, 2022). "XBP1 mRNA splicing was found to be increased in CD44hiCD24lo populations in triple-negative breast cancer, a stem-like cell population." (PMID 35349489, 2022). "A recent study revealed that an XBP1 gene signature was expressed at significantly higher levels in ERα+ or non-triple-negative breast cancer samples than in ERα- or triple-negative breast cancer samples, respectively." (PMID 33291081, 2020). "Recent studies found that XBP1 depletion from triple negative breast cancer cell models inhibited tumor growth and tumor relapse, and the active form of XBP1 was linked to the activation of HIF1α pathway and angiogenesis, and associated with poor prognosis." (PMID 32774853, 2020). "This agrees with a previous report where the poor prognosis of triple-negative breast cancers correlated with the assembly of a transcriptional complex of XBP1 and HIF1α." (PMID 28674530, 2017). "Since XBP1 is a known target of ERN1 and implicated in triple-negative breast cancer, we tested regulation of the gene by qPCR." (PMID 27829216, 2016). "A recent study provides intriguing evidence that, in triple-negative breast cancer, XBP1 plays a major role in promoting oncogenesis and cancer stem cell properties." (PMID 25927911, 2014). "Previous research has proved that UPR-related IRE1/XBP1 signaling pathway plays a role in tumor progression, with high expression of XBP1s protein correlating with poor prognosis in glioblastoma, triple-negative breast cancer, and pre-B acute lymphoblastic leukemia." (PMID 38700505, 2024). "The IRE1α-XBP1 axis is elevated in triple-negative breast cancer (TNBC)." (PMID 35884393, 2022). "XBP1 pathway activation has been shown to induce triple-negative breast cancer progression and is correlated with poor patient survival, suggesting that UPR inhibitors in combination with chemotherapy may improve tumor regression." (PMID 32138264, 2020). "To explore whether MALAT1 regulates proliferation and invasion abilities of triple-negative breast cancer cells through XBP1-HIF1α, we firstly detected the expressions of XBP1 and HIF1α in MDA-MB-231 by qRT-PCR after the knockdown of MALAT1." (PMID 29416769, 2018). "Another, more complex example is to administrate the peptide vaccine PVX-410 (derived from X-box-binding protein 1-unspliced XBP1-US, XBP1-spliced syndecan-1, and CS1), to treat triple-negative breast cancer tumors (NCT02826434)." (PMID 29312320, 2017). "In nematodes XBP-1 increases longevity and recent work suggests that XBP-1 binds to Hypoxia-inducible Factor 1α (HIF1α) to promote the growth of triple negative breast cancer." (PMID 26239352, 2015).
triple-negative breast carcinoma (continued). "Immunoblots confirmed previous results in XBP1 isoforms when comparing non-tumourigenic, Oestrogen receptor positive (ER+) and triple negative breast cancer cell lines (MCF10A, MCF7 and MDA-MB-231, respectively)." (PMID 31807121, 2019). "Moreover, in triple negative breast cancer in which ERα is absent, the IRE1/XBP1 axis plays a central role in tumorigenicity and progression, and the extent of activation of an XBP1 gene index is correlated with reduced patient survival." (PMID 29963013, 2018).
Hepatic steatosis (32 papers, 2012 to 2025). Steatosis is a term used to denote lipid accumulation within hepatocytes. "Concerning the therapeutic significance, we found that Xbp1 deficiency largely attenuated FFC diet-induced hepatic steatosis in mice." (PMID 39113706, 2024). "In a recent study, it was confirmed that the deacetylation of the X-box binding protein 1 (XBP1s) by SIRT6 can alleviate hepatic steatosis caused by endoplasmic reticulum stress." (PMID 33274005, 2020). "Interestingly, IRE1α-XBP1 signaling has been linked to hepatic steatosis, and inflammation in NAFLD." (PMID 33546405, 2021). "However, human nonalcoholic steatohepatitis (fatty liver with inflammation and fibrosis) is associated with inappropriately low levels of hepatic XBP1 expression compared with bland hepatic steatosis (fatty liver without inflammation and fibrosis)." (PMID 25617409, 2015). "Additionally, loss of SIRT6 induced hepatic steatosis through the deacetylation of X-box-binding protein 1 (XBP1s), a key modulator of ER stress, while SIRT6 overexpression prevented ER stress activation triggered by tunicamycin, a well-known ER stress inducer." (PMID 35743232, 2022). "During hepatic steatosis development, elevated GRP78 expression and increased formation of XBP1 mRNA splicing variants serve as hallmark indicators of ERS." (PMID 41010487, 2025). "Deletion of IRE1α-XBP1 in ERS promotes hepatic steatosis, whereas deletion of XBP1 has the same effect." (PMID 41031795, 2025). "Specific knockout of Xbp1 in macrophages exhibits M2 polarization in regulating hepatic steatosis, and engineered exosomes induce M2 polarization in macrophages for the treatment of rheumatoid arthritis." (PMID 39143545, 2024). "This impaired or dysregulated hepatic IRE1α/XBP1 pathway expression is consistent with previously reported findings in murine models of cholestasis and murine and human fatty liver disease." (PMID 36520816, 2022). "The rescue of Xbp1 activity in HFD-fed or ob/ob mice improves glucose homeostasis and reduces hepatic steatosis, which is associated with reductions in the expression of lipogenic genes." (PMID 32660130, 2020). "Among the three identified UPR signaling pathways, IRE1α reportedly contributes to the development of hepatic steatosis by upregulating genes involved in fatty acid and triglyceride synthesis by XBP-1." (PMID 30759889, 2019). "Collectively, we present direct evidence supporting the importance of XBP1 acetylation in ER stress-induced hepatic steatosis." (PMID 31541078, 2019). "Previous study reported that IRE1α contributed to the development of hepatic steatosis through upregulation of gene expression involved in fatty acid and triglyceride synthesis by XBP-1." (PMID 26540043, 2015). "While IRE1α itself is protective against ER-stress-induced lipogenesis and hepatic steatosis, its downstream mediator XBP1 promotes transcription of genes involved in fatty acid and cholesterol biosynthesis." (PMID 22195283, 2012). "Inhibition of XBP1 in hepatocytes alleviates liver steatosis and MASH." (PMID 39911797, 2025). "Moreover, FT@XBP1 alleviated hepatic steatosis, injury, and fibrosis in an FFC diet-induced MASH model, while the impact of FT@XBP1 on HSCs in vitro was almost negligible." (PMID 39113706, 2024). "Liver XBP-1 and eIF2α depletion is accompanied by decreased hepatic steatosis in obese animals." (PMID 38084147, 2023). "SIRT6-deacetylated X-box binding protein 1 (XBP1) is transactivated in Lys257 and Lys297, and promotes the degradation of XBP1s protein through the ubiquitin-proteasome system, thereby reducing endoplasmic reticulum stress and liver steatosis." (PMID 36008973, 2022). "Indeed, Xbp1 ablation has been reported to ameliorate liver steatosis and injury, as well as hyperlipidemia in ApoE(-/-) mice." (PMID 33467546, 2021).
Hepatic steatosis (continued). "Moreover, it has been shown that DHA ameliorates fructose-induced hepatic steatosis by modulating ER stress response (reducing Xbp1 mRNA and pIRE1α and IRE1α levels) in primary mouse hepatocytes." (PMID 33546405, 2021). "An upstream regulator analysis indicated that PPARα and XBP1 were the top 2 predicted transcription activators involved in the process of hepatic steatosis induced by OSI-906, whereas pathways related to SREBF2 and lysophosphatidylcholine were identified in the linagliptin-treated group." (PMID 33105604, 2020). "Apparently, the marked upregulation of xbp1 in our study might enhance hepatic lipogenesis and lead to subsequent liver steatosis." (PMID 32046144, 2020). "Whether the improvement of hepatic steatosis in these mouse models is a direct outcome of transcriptional regulation by Xbp1 or a secondary consequence of resolved metabolic stress and improved insulin sensitivity remains unclear." (PMID 32660130, 2020). "In NAFLD, the activity of inositol-dependent enzyme 1 (IRE1), X-box binding protein 1 (XBP1), and activating transcription factor (ATF6) is inhibited, and key enzymes of the lipid homeostasis pathway are downregulated, leading to hepatic steatosis." (PMID 37570615, 2023). "Studies have indicated that both IRE1α-XBP1 and PERK-EIF2 arms participate in hepatic steatosis through the regulation of DNL, lipogenesis, and very low-density lipoprotein secretion." (PMID 36501024, 2022). "For example, XBP1, as a regulator of ERS, can alleviate ERS and prevent hepatic steatosis, while in XBP1-knockout mice, long-term unrelieved ERS can promote hepatic steatosis." (PMID 36535923, 2022). "The active spliced form of X-box-binding protein 1 (XBP1) is deacetylated by SIRT6, which leads to XBP1 degradation and subsequent prevention of endoplasmic reticulum (ER) stress-induced hepatic steatosis." (PMID 36465178, 2022). "Dysregulation of the IRE1α/XBP1 pathway of the UPR, with a resultant inability to adequately resolve ER stress, as has been demonstrated in multiple murine models of liver disease including pharmacologic or fatty liver-induced ER stress." (PMID 36520816, 2022). "Direct enhancement of ER stress induced with chemical agents and genetic mutations of ER stress molecules (including PERK/eIF2α, IRE1/ X-box binding protein 1 (XBP1) and ATF6) stimulate hepatic steatosis via controlling lipid synthesis and the inflammatory response." (PMID 32521713, 2020). "XBP1 likely does not regulate ER stress-mediated steatosis as tunicamycin-induced fatty liver occurred both in the presence and absence of spliced XBP1." (PMID 22195283, 2012). "We noted that previous studies focusing on spontaneous XBP1 function were conducted in young mice at 3–4 months of age, and none of these earlier animal studies monitoring hepatic steatosis were aware of the robust 12-h clock rhythmicity that exists in the ER stress and UPR pathways." (PMID 33277471, 2020).